MYD88 (MYD88 innate immune signal transduction adaptor)
Diseases named in the same sentence as MYD88 in open-access papers (continued):
Sharing a sentence is not in itself a finding about the gene and the disease.
fibrosis (9 papers, 2013 to 2025). the formation of excess fibrous connective tissue in an organ or tissue in a reparative or reactive process. "However, far less is known about the function of MyD88 signaling-specific deficiency in HSCs in a fibrosis model." (PMID 35484116, 2022). "Here, we used a CCl4-induced mouse fibrosis model in which MyD88 was selectively depleted in qHSCs (GFAPMyD88−/− mice) or aHSCs (α-SMAMyD88−/− mice)." (PMID 35484116, 2022). "In this study, we used a carbon tetrachloride (CCl4)-induced mouse fibrosis model in which MyD88 was selectively depleted in myeloid cells." (PMID 34830293, 2021). "The late fibrosis group (F2-F4) showed significant up regulation of MyD88 transcript when compared to either healthy subjects or early fibrosis group (F0-F1) (p = 0.009 and 0.03, respectively)." (PMID 27135246, 2016). "Moreover, the deficiency of MYD88 signaling in B cells decreased the infiltration of dendritic cells and monocytes in CCL4-induced fibrosis mice." (PMID 38287425, 2024). "It demonstrated that intravenous administration of T. cruzi-derived neurotrophic factors in MyD88-knockout mice (deficient in TLR signaling) increased CX3CL1 and CCL2 levels, modulating inflammatory responses mediated by Trk signaling and reducing cardiac fibrosis." (PMID 40936920, 2025).
liver disease (9 papers, 2017 to 2025). "As outlined in the introduction, the TLR4/MyD88-dependent and TLR4/TRIF-dependent pathways are crucial contributors to increased inflammation during LPS-associated liver disease." (PMID 37446388, 2023). "Besides, the TLR4/MyD88/NF-κB signal mainly mediates the inflammatory response, and is a signal transduction pathway regulating liver diseases." (PMID 36311675, 2022). "Serum LPS levels, shown to increase throughout the time course of liver disease, were found to be negatively correlated with Tlr4 (R = − 0.97, P = 0.033) and Myd88 (R = − 0.71, P = 0.041); genes which are well established to be involved in macrophage mediated LPS immunotolerance." (PMID 33858327, 2021). "Myd88-mediated signaling activates downstream NF-κB and contributes to the immunosuppressive TME in liver diseases." (PMID 37968706, 2023). "S. mussotii appears to be effective for treating liver diseases, such as jaundice, and we propose that S. mussotii can be used to treat NAFLD rats under conditions of hyperlipidaemia by regulating the TLR4/MyD88/NF-κB pathway." (PMID 36205548, 2022). "LPS is related to the onset and progression of liver diseases and can activate the NFκB pathway via Toll‐like receptor 4 (TLR4) and myeloid differentiation 88 (MyD88)." (PMID 32652882, 2020). "However, the TLR4/MyD88-dependent and TLR4/TRIF-dependent pathways play significant roles in the escalation of inflammation in liver disease." (PMID 37446388, 2023).
marginal zone lymphoma (9 papers, 2017 to 2026). A usually indolent mature B-cell lymphoma, arising from the marginal zone of lymphoid tissues. "MYD88 mutations areslightly more frequent in marginal zone lymphoma (MZL) than CLL, but one of these two patients also harbored an SF3B1 mutation, which is far more frequent in CLL." (PMID 31590326, 2019). "Demonstration of the MYD88 p.L265P mutation may aid in the difficult differential diagnosis with nodal and extranodal marginal zone lymphomas (MZL) with plasmacytoid differentiation and plasma cell (multiple) myeloma." (PMID 35732829, 2022). "In the literature, MYD88 mutations have also been identified in marginal zone lymphoma (MZL), CLL, DLBCL and PCNSL." (PMID 30583461, 2018). "It is unclear whether a subset of the “lymphoplasmacytic lymphoma” cases in these series would still qualify as LPL or as marginal zone lymphoma now that MYD88 genetic testing has become available." (PMID 33322508, 2020). "We present a case illustrating the utility of MYD88 status in distinguishing atypical forms of WM from marginal zone lymphoma (MZL) and in selecting second-line therapy with ibrutinib." (PMID 28286680, 2017).
myocardial ischemia (9 papers, 2011 to 2025). A disorder of cardiac function caused by insufficient blood flow to the muscle tissue of the heart. "In addition, MyD88 inhibitors attenuated the infarct area during myocardial ischemia and reperfusion injury." (PMID 35692080, 2022).
subarachnoid hemorrhage (9 papers, 2017 to 2024). A serious neurological disorder characterized by intracranial hemorrhage into the subarachnoid space. "In addition, previous study found that miR-31-5p was involved in blood–brain barrier repair and Myd88/NF-κB pathway-mediated inflammation after subarachnoid hemorrhage." (PMID 35501920, 2022).
type 1 diabetes (9 papers, 2010 to 2025). "This is best illustrated by a study showing that diabetic mice deficient in the innate signaling molecule MyD88 are protected from the development of type 1 diabetes." (PMID 24410812, 2014). "In support of this possibility is the observation that NOD mice deficient in MyD88 gene expression have a distinct colonic microbiota profile from their heterozygote counterparts, ultimately influencing the clinical outcome of experimental type I diabetes." (PMID 21042588, 2010). "In the present study, both 7.0% w/w and 10.5% w/w FO feeding reversed STZ-induced hepatic inflammation by downregulating LPS/TLR4/MyD88 pathways, which indicated that FO supplementation may act as an anti-inflammatory food in the treatment of type 1 diabetes." (PMID 37685162, 2023). "MyD88 may also provide a therapeutic target in type I diabetes mellitus given the important role of IL-1β/MyD88-mediated signaling in this disease." (PMID 23305364, 2012). "Non-obese diabetic (NOD) mice, a model for type 1 diabetes, which lacks MyD88, an essential signaling component of innate immunity linking microbe-sensing immune receptors with immune signaling cascades is resistant to type 1 diabetes." (PMID 25628617, 2014). "MyD88-negative donors attenuate type 1 diabetes in germ-free NOD recipients." (PMID 29435463, 2017).
bacteremia (8 papers, 2010 to 2025). "Even though, TLR2 signaling plays a major role in the activation of B-1 cells, it is not the only TLR required for response against B. hermsii, as MyD88 knockout mice suffer from more severe episodes of bacteremia with B. hermsii than TLR2 knockout mice." (PMID 20625435, 2010). "Additionally, animal survival was improved and bacteremia was attenuated in the MyD88-/- (100%) and TLR2-/- (100%) mice in comparison with the irinotecan-injected WT mice (P<0.05)." (PMID 26440613, 2015).
cerebral infarction (8 papers, 2009 to 2025). An ischemic condition of the brain, producing a persistent focal neurological deficit in the area of distribution of the cerebral arteries. "In summary, our study determined that DPSCs‐Exos contributed to the inhibition of HMGB1/TLR4/MyD88/NF‐κB pathway and alleviated the cerebral I/R damage (including brain oedema, cerebral infarction and neurological deficit) in mice after tMCAO." (PMID 34231932, 2021). "We calculated the water content of brain tissue and the infarction size (as determined by TTC stain) to evaluate the influence of OMT on the expression of TLR4, TLR2, MyD88 and NF-κB in focal cerebral infarction in rats." (PMID 20182634, 2009). "In summary, ALO may reduce HI insult‐induced apoptosis and cerebral infarction by inhibiting glial cell activation and neuroinflammation mediated by the TLR4/MyD88/NF‐κB signaling pathway, thereby improving long‐term neurological function." (PMID 38888378, 2024). "One study showed that a congenital deficit of MyD88 failed to reduce cerebral infarct size in MyD88 knockout mice, but MyD88-dependent signaling contributes to the inflammatory responses induced by cerebral I/R." (PMID 36588708, 2022). "The experimental part of this study also showed that XNJ significantly improved the neural function of tMCAO mice, reduced the area of cerebral infarction, reduced inflammation-related factors such as TLR4, MyD88, NF-kappa B in ischemic site, and significantly reduced BBB permeability." (PMID 35646156, 2022).
endothelial dysfunction (8 papers, 2021 to 2026). In vascular diseases, endothelial dysfunction is a systemic pathological state of the endothelium (the inner lining of blood vessels) and can be broadly defined as an imbalance between vasodilating and vasoconstricting substances produced by (or acting on) the endothelium. "Activation of the TLR2 and TLR4 pathways by dentilisin leads to the upregulation of MyD88-dependent signaling, which triggers pro-inflammatory cytokines and excessive endothelial cell activation, contributing to endothelial dysfunction and CVD pathogenesis." (PMID 40136726, 2025). "Additionally, we confirmed the involvement of Gal-3 in A-ED, causing endothelial dysfunction, inflammation, and fibrosis in the penile corpus cavernosum through the TLR4/MyD88/NF-κB pathway." (PMID 38378809, 2024). "To ascertain whether TLR activation induces endothelial dysfunction in response to dietary cholesterol, we fed MyD88 KO mice a cholesterol rich diet." (PMID 34445361, 2021). "MyD88 KO-cholesterol fed mice were resistant to endothelial dysfunction in vivo." (PMID 34445361, 2021). "Additionally, we used MyD88 and MAPKAPK2/3 deficient mouse models to examine proteins upstream and downstream of p38α to better understand the role of innate immune signalling in the development of endothelial dysfunction in vivo." (PMID 34445361, 2021).
eosinophilia (8 papers, 2013 to 2025). "Results therefore indicate that ASD exacerbates lung eosinophilia in a MyD88-dependent pathway." (PMID 34333291, 2021). "Urban PM2.5 containing trace microbial elements may exacerbate allergic inflammation and eosinophilia in the murine lung via a TLR2/TLR4/MyD88-signaling pathway." (PMID 33809902, 2021). "In KSpn-mediated suppression of AAD we identified important suppressive roles for: TLR2 in eosinophil infiltration into the airways (partial) and AHR; TLR4 in eosinophilia of the airways and blood, IL-5 and IL-13 release from splenocytes and AHR, and; MyD88 in airway and blood eosinophilia and AHR." (PMID 27309732, 2016). "We also assessed the affects of TLR2, TLR4 and MyD88 on eosinophilia in the blood in AAD." (PMID 27309732, 2016). "Then in AAD we identified inductive roles for: TLR2 in IL-5 release from MLN T cells, IL-5 and IL-13 release from splenocytes and AHR; TLR4 in eosinophil infiltration into BALF and blood (partial) and AHR, and; MyD88 in blood eosinophilia, IL-13 release from MLN T cells and AHR." (PMID 27309732, 2016). "Therefore, the MyD88 adaptor molecule is essential to shift Bt-induced eosinophilia to airway neutrophilia in animals exposed to eLPS during sensitization." (PMID 23805294, 2013). "We found that eLPS did not suppress airway eosinophilia in MyD88- or IFN-γ ̃deficient mice while suppression was observed in mice deficient in CD14, TLR4 or TLR2 molecules." (PMID 23805294, 2013). "When WT, TLR 2(−/−), 4(−/−), and MyD88(−/−) BALB/c mice were IT challenged with OVA and/or AASD1, exacerbation of lung eosinophilia, increased Th2 cytokine and eosinophil-relevant chemokine production and induction of serum IgE and IgG were observed." (PMID 34333291, 2021). "The results of our study indicate that the murine lung eosinophilia exacerbated by co-exposure of LPS and H-ASD is not only mediated by TLR4/MyD88 signaling pathway, but also TLR4-independent signaling pathways." (PMID 31889961, 2019). "Specifically, the exacerbative effects of LPS and H-ASD on OVA-induced lung eosinophilia were investigated using wild-type (WT), TLR2−/−, TLR4−/− and MyD88−/− mice with BALB/c background." (PMID 31889961, 2019).
Granuloma (8 papers, 2012 to 2023). A compact, organized collection of mature mononuclear phagocytes, which may be but is not necessarily accompanied by accessory features such as necrosis. "The mice deficient in the innate immunity adapter proteins MyD88 and cytochrome B-245 beta chain (CybB) had larger and more granulomas compared to the wild-type mice injected with P. acnes." (PMID 33173621, 2020). "We have previously shown that certain TLR9 and/or MYD88 haplotypes are associated with diseases that are characterized by the presence of granulomas, such as Hodgkin's lymphoma and sarcoidosis." (PMID 28127112, 2016). "The possibility cannot be excluded, however, that the cellular components of H. polygyrus–induced granulomas differ in quality between MyD88-deficient and IL-1R1–deficient mice." (PMID 25114104, 2014). "Thus, the IL-1R–MyD88 pathway is implicated in inhibiting granuloma formation; however, protective immunity in MyD88-deficient mice appears to be granuloma independent." (PMID 25114104, 2014). "In addition, MyD88-deficient mice developed large numbers of granulomas along the intestinal wall in response to infection." (PMID 25114104, 2014). "Cytokines play a pivotal role in the development of granulomas while the significant task of activating the central immune response transcription factor NFκ-Β, is performed by MyD88." (PMID 28127112, 2016). "Our data support a link between MyD88, IL-1 and Th17 responses during the development of granulomas." (PMID 25050810, 2014). "While fibrosis was mainly localized in granulomas in WT animals, the pulmonary parenchyma of silica-treated MyD88-KO mice showed significant zones of less organized fibrosis." (PMID 25050810, 2014). "However, the levels of CXCL10 and CCL5, readout cytokines of the MyD88-independent TLR4 pathway increased at week 5 when Sj eggs induce granuloma and then at week 6 when Sj eggs induce acute liver damage." (PMID 29321784, 2017). "Granuloma formation was also less pronounced in MyD88-KO mice after silica." (PMID 25050810, 2014). "We demonstrated that MyD88 is crucial for the development of silicotic inflammation and granulomas." (PMID 25050810, 2014). "In WT mice, the fibrotic response was localized in granulomas where T regs accumulated, whereas it was less organized in MyD88-KO mice in the absence of a robust granuloma reaction." (PMID 25050810, 2014). "Surprisingly, MyD88−/−TRIF−/− mice developed far fewer granulomas than mice lacking only MyD88, suggesting that TRIF is required for the high numbers of granulomas observed in the absence of MyD88 or that it interacts with the pathways affected by loss of MyD88." (PMID 25114104, 2014).
keratitis (8 papers, 2010 to 2026). A corneal disease that is characterized by inflammation of the cornea. "Subsequent investigations into TLR activation in the mouse adenovirus keratitis model showed Src kinase associated activation of MyD88." (PMID 34960773, 2021). "Analogously, in the A. fumigatus keratitis model both Myd88- and Il1r1-deficient mice demonstrated reduced cellular infiltrate early after inoculation." (PMID 25629406, 2015). "Keratitis was reduced in MyD88 knockout mice, as well as in mice knocked out for both TLR2 and TLR9." (PMID 34960773, 2021). "Pharmacological inhibition of MyD88 was found to protect against renal injury induced by ischemia-reperfusion, both in vivo and in vitro, and MyD88 inhibitory peptide was shown to suppress adenovirus type 37-induced keratitis." (PMID 29144391, 2017). "Since MyD88 is critical for the generation of infectious keratitis via mediating TLR signaling, increased expression of MyD88 in peptides-treated HCEC suggests that TLRs pathways might also be involved in the response to these PhD peptides." (PMID 22428072, 2012). "In the current study, MyD88−/− mice had delayed cellular infiltration and unimpaired fungal growth, which is similar to the role of MyD88 in pulmonary aspergillosis, and indicates an essential role for this adaptor molecule in Aspergillus keratitis." (PMID 20617171, 2010). "In summary, we proved that thymol played a protective part in A. fumigatus keratitis by cutting down inflammatory cells aggregation, downregulating the TLR4/ MyD88/ NF-kB/ IL-1β signal expression and reducing necroptosis and pyroptosis." (PMID 36517045, 2023).
mantle cell lymphoma (8 papers, 2014 to 2023). Mantle cell lymphoma is a rare form of malignant non-Hodgkin lymphoma affecting B lymphocytes in the lymph nodes in a region called the ``mantle zone''. "LPS-pretreated TLR4-positive/myeloid differentiation 88 (MyD88)-positive mantle cell lymphoma(MCL) inhibited the proliferation and cytolytic activity of T cells by secreted IL-10 and VEGF, and triggers a cascade that leads to MCL growth and evasion from immune surveillance." (PMID 25299052, 2014).
mucositis (8 papers, 2014 to 2023). Mucositis is inflammation and damage of the mucous membranes lining the mouth and other parts of the gastrointestinal (GI) tract. "Therefore, the stimulation of the immune response by the intestinal microbiota via TLR/MyD88 and the activation of IL–1 family of cytokines, which also signal through MyD88 adaptor protein, seem to be relevant in the context of the mucositis associated with this anticancer treatment." (PMID 26440613, 2015). "The protective role of MyD88 and TLR2 and TLR9 in irinotecan-induced mucositis was associated with a pronounced reduction of the local inflammatory reaction, as detected by the measurement of myeloperoxidase activity and COX–2 and IL–1β production." (PMID 26440613, 2015). "In conclusion, treatment with glutamine was associated with up-regulation of TLR-4 and MyD88 expression and a concomitant decrease in intestinal mucosal injury caused by MTX-induced mucositis in a rat." (PMID 24742067, 2014). "In addition, similar to the TLR2-/- and TLR9-/- mice, the mice with a genetic deletion of MyD88 were markedly protected from the development of mucositis, as indicated by a reduced production of inflammatory markers and intestinal damage." (PMID 26440613, 2015).
Parkinson disease (8 papers, 2018 to 2025). A progressive degenerative disorder of the central nervous system characterized by loss of dopamine producing neurons in the substantia nigra and the presence of Lewy bodies in the substantia nigra and locus coeruleus. "In α-syn contexts relevant to Parkinson’s disease, HXT reduces the TLR4/MyD88 cascade that drives NF-κB/MAPK signalling and NLRP3 inflammasome activation, a central pathogenic axis produced during Parkinson’s disease." (PMID 41227598, 2025). "A recent study demonstrated that in Parkinson’s disease, SB improves brain function by inhibiting microglia-mediated neuroinflammation by TLR4/MyD88/NF-κB signaling pathway." (PMID 39962509, 2025). "We performed cell and animal experiments to explore the therapeutic effect of artemisinin on Parkinson's disease (PD) and the TLR4/Myd88 signaling pathway." (PMID 36691817, 2023). "Additionally, RA inhibited NF-κB nuclear expressions and downregulated the HMGB1, Myd88, and TLR4 expressions in cell and animal models of Parkinson’s disease." (PMID 34827094, 2021).
pneumococcal meningitis (8 papers, 2015 to 2025). An acute purulent infection of the meninges and subarachnoid space caused by Streptococcus pneumoniae, most prevalent in children and adults over the age of 60. "First, we comparatively monitored the course of experimental pneumococcal meningitis in WT, Tlr2/4–/–, Myd88–/–, and 3d/Tlr2/4–/– mice." (PMID 38358825, 2024). "The causative signals are mediated predominantly through TLR-recruited myeloid differentiation primary response adaptor 88 (MyD88), as indicated by a dramatic pneumococcal meningitis phenotype of Myd88–/– mice." (PMID 38358825, 2024). "CXCL16 was dependent on TLR2/4 and MyD88 signaling for neutrophil recruitment in the cerebrospinal fluid of patients and mice with pneumococcal meningitis." (PMID 37160878, 2023).